CP (ceruloplasmin)
Diseases named in the same sentence as CP in open-access papers (continued):
Sharing a sentence is not in itself a finding about the gene and the disease.
vasculitis (2 papers, 2024). "Our data confirm that low ceruloplasmin levels are associated with worse outcome in patients with anti-MPO vasculitis." (PMID 39388433, 2024). "This study suggests that a low serum ceruloplasmin level at diagnosis of anti-MPO ANCA-associated vasculitis is associated with a worse survival." (PMID 39388433, 2024). "Because of its ability to inhibit MPO activity, we hypothesized that a low serum ceruloplasmin level could be associated with more severe vasculitis and worse prognosis." (PMID 39388433, 2024). "The objective of this study was to determine whether serum ceruloplasmin level at diagnosis had a prognostic impact in patients with anti-MPO antibody-positive vasculitis." (PMID 39388433, 2024).
acute graft versus host disease (1 paper, 2013). A syndrome of immunologically mediated tissue damage that may occur following an allogeneic transplant, usually affecting the skin, liver, and GI tract. "Ceruloplasmin level increases in various acute inflammatory conditions, including acute graft-versus-host-disease (aGvHD) after allogeneic hematopoietic stem cell transplantation, cancer, and cardiovascular disease." (PMID 24206753, 2013).
Acute hepatic failure (1 paper, 2023). Hepatic failure refers to the inability of the liver to perform its normal synthetic and metabolic functions, which can result in coagulopathy and alteration in the mental status of a previously healthy individual. "A serum CP cut-off value of 16 mg/dL resulted in the highest diagnostic accuracy of WND in patients with acute hepatic failure." (PMID 37296680, 2023).
adenoma (1 paper, 2022). A neoplasm arising from the epithelium. "Comparing CRC to adenoma samples, some blood particles were still upregulated in CRC patients with CP, HP, and SERPINA3 displaying the largest difference." (PMID 36369736, 2022).
alcoholic liver diseases (1 paper, 2014). A disorder caused by damage to the liver parenchyma due to alcohol consumption. "The most important alterations observed in alcoholic liver disease are desialylation of transferrin and also haptoglobin, alpha 1-antitrypsin, and ceruloplasmin." (PMID 24959592, 2014).
Allergy (1 paper, 2019). An allergy is an immune response or reaction to substances that are usually not harmful. "After adjusting the model according to maternal allergy, the CB CCL17 level remained an independent factor that significantly correlated to CP-DEI, whereas family size and cat ownership during pregnancy were inversely correlated to CP-DEI." (PMID 31719945, 2019).
anaphylaxis (1 paper, 2016). An acute hypersensitivity reaction that occurs from exposure to an allergen. "Interestingly, the quotient sIgE CAS/sIgE BLG in the patients with the GI allergy phenotype was always lower than 1 (average 0.3) compared to those subjects with anaphylaxis, with a quotient higher than 1, given that their dominant allergenic CP is casein." (PMID 26909103, 2016).
ANCA-associated vasculitis (1 paper, 2024). "Based on our study’s results, decreased ceruloplasmin levels appear to be a marker of poor prognosis in anti-MPO ANCA-associated vasculitis." (PMID 39388433, 2024). "Moreover, serum level of ceruloplasmin can be influenced by many parameters, such as systemic inflammation, hepatic and renal functions, which are frequently disturbed in ANCA-associated vasculitis." (PMID 39388433, 2024).
Arthritis (1 paper, 2020). Inflammation of a joint. "Although classical (CP) and lectin (LP) routes of complement activation alone seem not to be essential in the pathogenesis of arthritis, there is a link between the AP and LP." (PMID 33274243, 2020).
Ataxia (1 paper, 2023). Ataxia refers to impaired coordination of voluntary muscle movement. "Recently, intraperitoneal administration of CP to Cp-KO mice has been shown to cross the barrier and penetrate into the brain, restore ferroxidase activity, reduce iron accumulation in the brain, restore neuronal loss, and improve ataxia." (PMID 36768886, 2023).
atransferrinemia (1 paper, 2018). Congenital atransferrinemia is a very rare hematologic disease caused by a transferrin (TF) deficiency and characterized by microcytic, hypochromic anemia (manifesting with pallor, fatigue and growth retardation) and iron overload, and that can be fatal if left untreated. "Aceruloplasminemia and atransferrinemia are further inherited disorders of iron overload caused by deficiency in ceruloplasmin or transferrin, the plasma ferroxidase and iron carrier, respectively." (PMID 30420953, 2018).
atrial fibrillation (1 paper, 2021). A disorder characterized by an electrocardiographic finding of a supraventricular arrhythmia characterized by the replacement of consistent P waves by rapid oscillations or fibrillatory waves that vary in size, shape and timing and are accompanied by an irregular ventricular response. "When studying the associations of the genetic variants concentration of ceruloplasmin and the occurrence of atrial fibrillation, it was shown that these variants are associated with an increased concentration of ceruloplasmin in the blood, but at the same time reduce the risk of fibrillation." (PMID 34948066, 2021).
autoimmune encephalitis (1 paper, 2020). Inflammation of the brain secondary to an immune response triggered by the body itself. "The blood count, morphology of erythrocyte, blood biochemistry, ceruloplasmin, thyroid function, parathyroid hormone, metal toxin analysis, ganglioside antibody spectrum, paraneoplastic antibody spectrum, and antibodies of autoimmune encephalitis were normal." (PMID 32307925, 2020).
B-acute lymphoblastic leukemia (1 paper, 2014). "CP growth inhibitory activity was measured on primary cultures derived from pediatric patients affected by B-acute lymphoblastic leukemia." (PMID 24980813, 2014). "In well agreement with results obtained on stabilized cell lines, CP induced ER-stress and apoptosis also in primary cells from B-acute lymphoblastic leukemia patients." (PMID 24980813, 2014).
basal cell carcinoma (1 paper, 2017). A carcinoma involving the basal cells. "One of the CP pathways was associated with FNBMD (“basal cell carcinoma”, Q = 0.02) when allowing a 20 kilobase (kb) window around genes." (PMID 28934396, 2017).
bile duct tumors (1 paper, 2023). "Lung, epithelial ovarian, colon, and bile duct tumors also have high serum CP levels." (PMID 37637428, 2023).
Blindness (1 paper, 2022). Blindness is the condition of lacking visual perception defined as a profound reduction in visual perception. "However, to our knowledge, few studies have focused on whitening agents’ release and skin delivery behaviors from CP hydrogel based on drug–enhancers–CP (skin) interactions, which has resulted in blindness and uncertainty regarding the utilization of enhancers in whitening formula optimization." (PMID 35213995, 2022).
bronchiolitis (1 paper, 2020). Inflammation of the bronchioles characterized by swelling of the bronchioles and mucus accumulation. "Analyzing data by sex, CP• amount was not significantly different between HC children, as well as between patients with bronchiolitis, although in these latter the CP• mean value was higher in boys." (PMID 32143677, 2020).
bruxism (1 paper, 2025). Excessive clenching of the jaw and grinding of the teeth. "The findings of the study showed decreased levels of arginase 1 and ceruloplasmin, suggesting an association between tooth grinding and enzymes involved in the nitric oxide pathway, irrespective of bruxism severity." (PMID 40990027, 2025). "Results for Arg1 and ceruloplasmin in bruxers and nonbruxers, differentiated based on bruxism severity." (PMID 40990027, 2025). "The results showed that the concentration of Arg1 and CP was significantly lower in individuals with SB, irrespective of bruxism severity." (PMID 40990027, 2025). "Regression analysis revealed that only in the group of patients with higher Arg1 and CP concentrations, was there a negative linear relationship with the bruxism episode index (BEI)." (PMID 40990027, 2025). "The results of this study demonstrated that Arg1 and CP concentrations in the serum were significantly lower in individuals with SB, independent of the severity of bruxism." (PMID 40990027, 2025). "The results of this study showed that Arg1 and CP concentrations were significantly lower in individuals with SB, independent of bruxism severity." (PMID 40990027, 2025).
Bull's eye maculopathy (1 paper, 2023). Progressive maculopathy characterized by concentric regions of hyper- and hypopigmentation, with an initial foveal sparing and whose appearance is said to resemble the central target of a dart board. "In this study, liver-specific Hepc KO (Cre+ Hepcf/f) mice were crossed with Cp KO (Cp−/−) mice to test the hypothesis that low levels of CP would exacerbate the toxicity of high iron levels and cause more severe degeneration, thus modeling the situation in the patient with bull's eye maculopathy." (PMID 37439255, 2023). "This study confirms that the combination of elevated iron levels and reduced CP levels contributed to bull's eye maculopathy in the HH patient mentioned in the introduction." (PMID 37439255, 2023). "It was hypothesized that the combination of low CP and high iron resulted in the bull's eye maculopathy." (PMID 37439255, 2023).
B‐cell CLL (1 paper, 2020). "Investigations with regard to the correlation between LINC00176 and promoter region of CP turned out to be positive via B‐cell CLL/lymphoma 3 (BCL3) by means of dual‐luciferase reporter gene assay, ChIP and RIP assays." (PMID 31668012, 2020).
cardiac arrest (1 paper, 2018). Cessation of breathing and/or cardiac function. "The CP-Tg mice showed resistance to ischemia and death in the Rose Bengal/laser- and AA-induced thrombotic stroke and cardiac arrest models, as well as resistance to angiotensin-induced vascular damage." (PMID 29374184, 2018). "However, thrombotic stroke and cardiac arrest leading to death was dramatically delayed in CP-Tg mice until they were given an average of 100 mg/kg of AA (LD50 = 50 mg)." (PMID 29374184, 2018).
Cerebral atrophy (1 paper, 2023). Atrophy (wasting, decrease in size of cells or tissue) affecting the cerebrum. "Alzheimer patients with elevated non-ceruloplasmin bound Cu showed a less severe cerebral atrophy, suggestive of a distinct role of mobile Cu for the disease process." (PMID 37886755, 2023).
cerebral malaria (1 paper, 2013). A sequestration of Plasmodium falciparum in the brain, which can cause coma and/or seizures. "An increase in orosomucoid 2, differentially expressed in both plasma and CSF of patients with cerebral malaria, together with an increased production of ceruloplasmin and glutathione, would enhance antioxidant defenses and limit the stimulatory effects of oxidant molecules on cytokine production." (PMID 23888081, 2013).
Chlamydia infection (1 paper, 2023). "We found that different subgroups of Chlamydia infection had different responsible pathogen profiles, with 11, 6, and 11 responsible pathogens detected in the CP, CA, and PA groups, respectively." (PMID 37434780, 2023). "To further investigate the effect of Chlamydia infection on the lung microbiota, we performed a comparative analysis of the microbial communities of 40 BALF samples from different Chlamydia infection subgroups (CP and PA groups) and clinical control groups (O and N groups)." (PMID 37434780, 2023).
chordoma (1 paper, 2021). Chordomas are rare malignant tumors arising from embryonic remnants of the notochord in axial skeleton. "These patients, labeled CP(io), had recurrent chordoma and had undergone various treatment modalities (refer to Materials and Methods) prior to providing blood for this study." (PMID 35765577, 2021).
chronic liver failure (1 paper, 2018). Liver failure that develops slowly and gradually for some time, possibly for years, often as the result of cirrhosis, or malnutrition. "Patients with acute and subacute, chronic liver failure had the lowest mean serum CP (200.8±55.3 mg/L, 218.6±73.8 mg/L, respectively); 53.0% of patients with acute and subacute liver failure had CP <200 mg/L and 12.6% had CP <150 mg/L." (PMID 29324775, 2018).
cold agglutinin disease (1 paper, 2019). Cold agglutinin disease is a type of autoimmune hemolytic anemia defined by the presence of cold autoantibodies (autoantibodies which are active at temperatures below 30B0C). "Antibodies against C1s are being used successfully to suppress CP-triggered cold-agglutinin disease and might reasonably have efficacy in preventing atheroma formation." (PMID 31555668, 2019).
cutaneous papilloma (1 paper, 2021). "MDA may be a more sensitive indicator for cutaneous papilloma in cattle than SOD, CAT, and ceruloplasmin." (PMID 34722735, 2021).
cyst (1 paper, 2021). A sac-like closed membranous structure that may be empty or contain fluid or amorphous material. "Such comparison resulted in 4 upregulated (CP, CEACAM5, DMBT1, and KRT6A) and 8 downregulated (CEL, CPA1, CPB1, ALB, SERPINA4, CA2, CLU, and AMBP) DEGs secreted in cyst fluid of high-risk IPMNs." (PMID 34790815, 2021).
cystitis (1 paper, 2024). Inflammation of the urinary bladder. "The results of first morning urine test in rats performed using urine test strips and microscopic examination of urine sediment proved that cystitis was induced in rats after intraperitoneal administration of three doses of CP (each dose being equal to 50 mg/kg body weight)." (PMID 39451530, 2024).
diabetic neuropathy (1 paper, 2014). A chronic, pathological complication associated with diabetes mellitus, where nerve damages are incurred due to diabetic microvascular injury involving small blood vessels that supply these nerves, resulting in peripheral and/or autonomic nerve dysfunction. "While serum ceruloplasmin is an acute-phase reactant (levels rise during acute inflammation), serum ceruloplasmin levels may also be a marker of oxidative neuronal injury, as in diabetic neuropathy.." (PMID 25144566, 2014).
Down syndrome (1 paper, 2025). "Although there is no change in Cu CSF levels in AD, there is a lower percentage of holo-ceruloplasmin (active form) in the CSF but no change in ceruloplasmin level or activity, similarly to what is seen in patient with Down syndrome." (PMID 40847318, 2025).
dysplasia (1 paper, 2024). A usually neoplastic transformation of the cell, associated with altered architectural tissue patterns. "In addition, CPN mice displayed oral cavity squamous cell carcinoma (OSCC); CP mice bearing wild-type NRF2 expression did not develop oral cavity hyperplasia, dysplasia or OSCC." (PMID 38335300, 2024).
enteritis (1 paper, 2022). Inflammation of the small intestine. "Together, this study showed that CP-spor-super vaccines reduced NE histopathology and productivity loss, suggesting that C. perfringens sporulation plays an essential role on mediating the enteritis." (PMID 35744628, 2022).
eosinophilia (1 paper, 2022). "In particular, we detected upregulation of certain protein species of APOA1, APOC-II, and APOC-III, which resulted as negatively correlated with peripheral eosinophilia (cell/mm3%) and upregulation of certain protein species of the antioxidants ceruloplasmin and transthyretin." (PMID 35453511, 2022).
epidermodysplasia verruciformis (1 paper, 2005). A rare inherited genodermatosis characterized by chronic infection with human papillomavirus (HPV) leading to polymorphous cutaneous lesions and high risk of developing non melanoma skin cancer. "The CP primers were originally designed to amplify all the epidermodysplasia verruciformis-associated HPV types, but under modified conditions a large spectrum of mucosal types are amplified as well." (PMID 15642157, 2005).
fetal growth restriction (1 paper, 2021). A fetus that does not grow beyond the 10th percentile of conventionally accepted weight for gestational age. "At a false positive rate of 10%, ceruloplasmin could have predicted between 60% and 78% of the PE and/or fetal growth restriction cases at 20–24 weeks and 30–34 weeks of gestation, respectively." (PMID 34682802, 2021).
gallstones (1 paper, 2025). Solid crystalline precipitates in the biliary tract, usually formed in the gallbladder, resulting in the condition of cholelithiasis. "In biliary system stones, common bile duct stones are marked by elevated levels of β2-microglobulin and total bilirubin, while gallstones are associated with increased levels of basophils, ceruloplasmin, ferritin, immunoglobulin-A, and rheumatoid factor." (PMID 40551898, 2025). "In biliary system stones, the characteristic feature of common bile duct stones is an increase in β2-microglobulin and total bilirubin levels, while gallstones are associated with elevated counts of basophils, ceruloplasmin, ferritin, immunoglobulin-A, and rheumatoid factor levels." (PMID 40551898, 2025).
HCMV infection (1 paper, 2022). "Cytotect CP® neutralizes HCMV infection of fibroblasts and epithelial cells in vitro." (PMID 35456746, 2022).
hematoma (1 paper, 2016). A hematoma is a collection of blood from a vascular structure into an extravascular space. "Fourthly, we found that intraventricular hemorrhage, hematoma volumes and surgery treatments have different associations with the contents of iron, ferritin, Tf and CP in the serum at different stages after ICH in patients." (PMID 26898550, 2016). "We also examined the effects of intraventricular hemorrhage, hematoma volumes and surgery treatment on the contents of iron, ferritin, Tf and CP in the serum." (PMID 26898550, 2016). "We also used Spearman correlation coefficient to determine whether there is a correlation between hematoma volume and serum iron, ferritin, Tf or CP contents collected at day 1 in 100 patients." (PMID 26898550, 2016). "In addition, we used Spearman correlation coefficient to determine the association of these indicators of iron metabolism we measured with relative edema volume, relative edema ratio and hematoma volume as well as serum iron with ferritin, CP or Tf, and ferritin with Tf contents." (PMID 26898550, 2016). "We also compared the changes in the contents of serum iron, ferritin, Tf and CP in patients with (IVH) or without intraventricular hemorrhage (No-IVH), larger (≥30 ml) or smaller (<30 ml) hematoma volume, having received surgery (Surg-P) or conservative treatments (Cons-P)." (PMID 26898550, 2016).
hemolysis (1 paper, 2022). Disruption of the integrity of the erythrocyte membrane causing release of hemoglobin. "In the classic case of ALF-WD, the sudden release of copper from the liver leads to high levels of non-ceruloplasmin-bound copper in plasma, resulting in excessive destruction of red blood cells, which further leads to intravascular hemolysis." (PMID 36210929, 2022).
hypercortisolemia (1 paper, 2012). "This is because of hypercortisolemia which stimulates the synthesis of Cu containing protein ceruloplasmin and Zn binding protein metallothionein in liver and other tissues." (PMID 22992416, 2012).
Hypoalbuminemia (1 paper, 2019). The concentration of albumin in the blood circulation is below the lower limit of normal. "Haptoglobin and ceruloplasmin increased as acute phase reaction proteins; alpha-2 macroglobulin increased in a compensatory manner to maintain plasma colloid osmotic pressure due to hypoalbuminemia." (PMID 31357953, 2019).
inflammatory bowel disease (1 paper, 2014). A spectrum of small and large bowel inflammatory diseases of unknown etiology. "It is interesting to note that ceruloplasmin recently has been shown to be protective in mouse models of inflammatory bowel disease, where IL-22 has also been shown to be protective." (PMID 24498387, 2014).